FLNA (filamin A)
Diseases named in the same sentence as FLNA in open-access papers (continued):
Sharing a sentence is not in itself a finding about the gene and the disease.
congenital heart disease (3 papers, 2020 to 2023). A heart disease that is present at birth. "FLNA mutation causes rare but progressive PAH in addition to a wide spectrum of congenital heart disease and other comorbidities in pediatric patients." (PMID 33143682, 2020). "In addition, PAH in pediatric patients with FLNA mutation was fatal despite of their congenital heart disease (CHD), and required early lung transplantation." (PMID 33143682, 2020).
congenital short bowel syndrome (3 papers, 2020 to 2025). Congenital short bowel syndrome is a rare intestinal disorder of neonates of unknown etiology. "We report the case of a male infant with an FLNA nonsense mutation (c.5265C>G; p.Tyr1755*), whose phenotype was characterized by the canonical features of bilateral PNH, a perimembranous VSD, and congenital short bowel syndrome (CSBS)." (PMID 41555926, 2025). "Mutations specifically affecting the long isoform of filamin A are associated with congenital short bowel syndrome without neurological features." (PMID 40860336, 2025). "Beyond the OPDSDs, FLNA variants have also been shown to cause XCVD, PVNH1 and PVNH4, childhood interstitial lung disease (ChILD), structural cardiac and aortic anomalies, thoracic aortic aneurysms (TAA), chronic intestinal pseudo-obstruction (CIPO), and congenital short bowel syndrome (CSBS)." (PMID 32085749, 2020).
cryptorchidism (3 papers, 2019 to 2020). The failure of one or both testes of a male fetus to descend from the abdomen into the scrotum during the late part of pregnancy. "Among the eighteen genes, four have been previously identified in patients with hypospadias (CYP1A1, FLNA, GLI3, and GLI2), three have been reported to be associated with cryptorchidism (FLNA, RET, and PTPN11), and one has been identified in patients with micropenis (EVC)." (PMID 33424767, 2020).
heart failure (3 papers, 2022 to 2024). Inability of the heart to pump blood at an adequate rate to meet tissue metabolic requirements. "Loss of FLNA results in vascular defects and cardiac structural and functional defects, leading to a heart failure phenotype." (PMID 38310240, 2024). "FLNA, ITGA6, ITGA1, and MDK may play an important role in neurons in heart failure with DCM." (PMID 38310240, 2024).
otopalatodigital syndrome type 1 (3 papers, 2016 to 2023). The mildest form of otopalatodigital syndrome spectrum disorder that is characterized by a generalized skeletal dysplasia, mild intellectual disability, conductive hearing loss, and typical facial anomalies. "MNS, an extremely rare skeletal anomaly belonging to one of the otopalatodigital spectrum disorders (OPDSD), is the most severe disease that causes a lethal phenotype in hemizygous males and skeletal dysplasia in heterozygous survivable females since gain‐of‐function mutations in FLNA." (PMID 36734119, 2023).
prostate adenocarcinoma (3 papers, 2019 to 2024). "The overall Filamin A expression was slightly more in prostatic adenocarcinoma of African American patients than that of Caucasian patients." (PMID 30623593, 2019). "Filamin A expression was observed in 25% (2/8) of tumors in both African American (n = 8) and Caucasian patients (n = 8) with prostatic adenocarcinoma." (PMID 30623593, 2019). "However, we observed a decrease in Filamin A expression in prostatic adenocarcinoma as compared to benign or normal glands in both African American and Caucasian patients." (PMID 30623593, 2019).
prune belly syndrome (3 papers, 2020 to 2023). "Prune belly syndrome (PBS) is a rare, multisystem congenital myopathy characterized by dysfunction of the X-chromosome gene filamin A (FLNA) in transmitting force signals from the actin-myosin motor units and cytoskeleton to the extracellular matrix." (PMID 37691828, 2023).
schizophrenia (3 papers, 2014 to 2025). A major psychotic disorder characterized by abnormalities in the perception or expression of reality. "In our research, the differential proteins neural cell adhesion molecule L1, integrin alpha-M, alpha-actinin-1, filamin A, and profilin-1 are nominated as schizophrenia-associated candidates." (PMID 41573035, 2025). "Our research indicates that neural cell adhesion molecule L1, integrin alpha-M, alpha-actinin-1, filamin-A and profilin-1 which are associated with cytoskeleton, synapse and immunity were preliminarily screened as candidate protein markers for schizophrenia." (PMID 41573035, 2025). "The genetic interaction for mitochondria function and schizophrenia were illustrated by DRD2 linked to NDUFS7 through protein-protein interactions of FLNA and ARRB2." (PMID 25522158, 2014). "The genetic interaction between mitochondria function and schizophrenia may be revealed by DRD2 linked to NDUFS7 through protein-protein interactions of FLNA and ARRB2." (PMID 25522158, 2014). "There are relatively few studies on the levels of filamin A in schizophrenia." (PMID 41573035, 2025). "This study suggests that proteins associated with the cytoskeleton, synapse, and immunity are related to schizophrenia, in particular neural cell adhesion molecule L1, integrin alpha-M, alpha-actinin-1, filamin A, and profilin-1, which are expected to be candidate protein markers for schizophrenia." (PMID 41573035, 2025). "In addition, the dopamine hypothesis is well known as one of the widely accepted pathogeneses of schizophrenia, and the dopamine signaling pathway is regulated by filamin A. Our research findings indicate that filamin A may play a certain regulatory role in schizophrenia." (PMID 41573035, 2025).
seminoma (3 papers, 2020 to 2024). A radiosensitive malignant germ cell tumor found in the testis (especially undescended), and extragonadal sites (anterior mediastinum and pineal gland). "In order to elucidate functions of FLNA in seminoma cells, we have generated FLNA-deficient TCam-2 cells." (PMID 33266100, 2020). "Additionally, FLNA-deficient human seminoma cells exhibited irregular organization of F-actin and impaired cell motility." (PMID 39399465, 2024). "Whatever the mechanism of decreased expression of filamin A, it increases the DNA repair capacity of the cell—a condition that worsens the responsiveness of CS I seminoma patients to DSB-based therapy." (PMID 34771736, 2021). "Of them, 14-3-3γ, ezrin, filamin A, Parkinsonism-associated deglycase 7 (PARK7), vimentin and vinculin, were validated in CS I seminoma patient cohort." (PMID 34771736, 2021). "This implicates a potential of filamin A to serve as a marker for prognosis of CS I seminoma patients that are managed by DSB-based therapy." (PMID 34771736, 2021). "Taken together, the results obtained in this study imply that FLNA is critically involved in the cellular phenotype and growth of the seminoma cell line TCam-2, and possibly also plays an important regulatory role in human seminomas." (PMID 33266100, 2020). "In summary, our data suggest that FLNA is crucially involved in balancing stem cell characteristics and invasive properties in human seminoma cells and possibly human testicular germ cells." (PMID 33266100, 2020). "In summary, our data provide evidence that FLNA is crucially involved in balancing stem cell characteristics and invasive properties in human seminoma cells, and possibly human spermatogonial cells and SSCs." (PMID 33266100, 2020). "Therefore, both the epigenetic status of the FLNA promoter and expression of the TRIM44-SQSTM1/p62-filamin A protein loop represent potential targets for therapy-resistant CS I seminomas." (PMID 34771736, 2021). "In filamin A-deficient TCam-2 seminoma cells, enhanced transcript levels of the pluripotency factors OCT3/4, NANOG and FGFR3 compared to filamin A-proficient cells have been found, indicating that filamin A is involved in determining stemness in seminomas." (PMID 34771736, 2021). "It seems that deregulated expression of filamin A, PARK7 and 14-3-3γ in RTI-positive CS I seminoma might be implicated in the pathogenesis and progression of this disease and may help to identify patients with poor prognosis." (PMID 34771736, 2021). "What is the molecular basis of decreased expression of filamin A in RTI-positive CS I seminoma?" (PMID 34771736, 2021). "If this assumption is true, filamin A may critically be involved in stem cell characteristics and invasiveness/metastasis in CS I seminomas." (PMID 34771736, 2021). "Our data displaying significantly decreased expression of filamin A in CS I seminomas with RTI parallels a situation in BC, where filamin A down-regulation stimulates cancer cell migration, invasion and metastasis." (PMID 34771736, 2021). "While 14-3-3γ, ezrin, filamin A, PARK7, vinculin and vimentin could be analysed in cohort of CS I seminoma patients using IHC to validate their clinical relevance, IHC evaluation in the case of caldesmon and 14-3-3β failed (data were non-homogenous and suboptimal)." (PMID 34771736, 2021). "Assuming that RTI positivity predicts the presence of occult (micro)metastases at diagnosis, our data showing virtually no change in filamin A subcellular localization upon RTI does not support a role of intracellular localization for filamin A in metastatic spread in CS I seminomas." (PMID 34771736, 2021). "Notably, RTI-positive CS I seminomas showed decreased expression of PARK7 and filamin A, when compared with -negative cases." (PMID 34771736, 2021).
Sepsis (3 papers, 2024 to 2025). Sepsis is defined as life-threatening organ dysfunction caused by a dysregulated host response to infection. "This case expands the phenotypic spectrum of FLNA deficiency, linking a nonsense mutation to a severe clinical course with fatal complications such as necrotizing enterocolitis and sepsis, highlighting the need for vigilant multi-organ monitoring." (PMID 41555926, 2025).
aortic regurgitation (2 papers, 2024 to 2025). "The other case presents a 37-year-old with a heterozygous pathogenic variant of FLNA (filamin A), diagnosed with mild mitral and aortic regurgitations and a mild ascending aortic aneurysm, who also underwent a cesarean section." (PMID 40722806, 2025). "Three patients had polymorphisms in filamin A (FLNA) with one patient having mild aortic regurgitation and another patient having mitral valve anterior leaflet prolapse, moderate mitral valve regurgitation and mild aortic and pulmonary regurgitation." (PMID 38562189, 2024).
astrocytoma (2 papers, 2016 to 2018). "Given our results that showed positive correlations among cytoplasmic Rac1, FLNa, and integrin β2, it is likely that FilGAP may serve as a key regulator for modulation of Rac1 activity through its interaction with the FLNa/integrin β2 axis in astrocytoma cells." (PMID 27790861, 2016). "In this study, we investigated the expression of FilGAP, with reference to the status of its related molecules, including FLNa, integrin β2, and Rac1, as well as the expression of ECT 2, cell proliferation, and IDH1 gene status in astrocytomas." (PMID 27790861, 2016).
bladder tumor (2 papers, 2013 to 2023). "The proteomic approach identified differential expression of proteins previously linked with aggressive clinical outcome in bladder tumors: gelsolin, moesin, Ezrin, caveolin, Filamin A." (PMID 23308193, 2013). "qRT-PCR demonstrated that the mRNA expression levels of ACTA2, FLNA, TAGLN, and TPM1 in bladder tumor cells were significantly decreased compared with normal bladder cells, which corresponded to the results of our prior bioinformatic investigation using public datasets." (PMID 37274283, 2023). "In addition, qRT-PCR and Western blotting demonstrated that the transcription and translation levels of ACTA2, FLNA, TAGLN, and TPM1 were much lower in bladder tumor cells than in normal bladder cells." (PMID 37274283, 2023).
cardiomyopathy (2 papers, 2020 to 2025). A disease of the heart muscle or myocardium proper. "This is particularly pertinent in genes with variable penetrance or dual-phenotypic overlap, such as FLNA (neurovascular/cardiac), DSP (aortic/cardiomyopathy), or PRDM5 (ocular/aortic)." (PMID 40981152, 2025).
cardiovascular malformations (2 papers, 2021 to 2024). "If such critical FLNA mutations are identified, patients can be informed that they run a higher risk of developing cardiovascular malformations, and can therefore be closely followed up by routine biochemical and radiological examinations." (PMID 34207234, 2021).
cognitive disorders (2 papers, 2025). A disease affects cognitive processes. "The wide range of symptoms, including dysmorphism, seizures, developmental delays and cognitive impairments, underscores FLNA’s pivotal role in orchestrating complex developmental processes." (PMID 40365811, 2025). "Additionally, we observed elevated lysosomal-associated membrane protein 1 (LAMP1) and reduced levels of filamin A and RAB7 (a member of the RAS oncogene family) in the pre-AD mild cognitive impairment group." (PMID 40772191, 2025).
diabetes (2 papers, 2023). "Since platelet P2Y12 signaling is activated in patients with diabetes, it is possible that under hyperglycemic environment, filamin A, which is activated by the activation of P2Y12 signaling, mediates platelet activation in concert with vinculin." (PMID 36831080, 2023).
emphysema (2 papers, 2021 to 2022). "Pathogenic variants of the X‐linked FLNA gene encoding filamin A protein have been associated with a wide spectrum of symptoms, including the recently described pulmonary phenotype with childhood‐onset panlobular emphysema." (PMID 35156755, 2022). "A loss-of-function mutation of the FLNA gene was reported in family adults with emphysema." (PMID 34828448, 2021).
FG syndrome (2 papers, 2021 to 2025). "FLNA has been previously reported as an X-linked recessive genetic factor associated with FG syndrome and CHD." (PMID 40406060, 2025).
Fibroadenoma (2 papers, 2020 to 2024). A benign tumor of the breast characterized by the presence of stromal and epithelial elements. "We detected an increase in the expression of six proteins (NUDT19, FBN1, NONO, FLNA, SCPEP1, and galactosidase alpha) in fibroadenoma." (PMID 33194682, 2020).
filaminopathies (2 papers, 2017 to 2025). "Mutations in the filamin A (FLNA) gene cause a broad range of disorders, affecting musculoskeletal, nervous, vascular, and gastrointestinal systems, collectively known as filaminopathies." (PMID 40860336, 2025).
interstitial lung disease (2 papers, 2020 to 2024). A diverse group of lung diseases that affect the lung parenchyma. "Of interest, mutations in the FLNA gene result in interstitial lung disease, a severe respiratory illness." (PMID 32302349, 2020).
intestinal pseudo-obstruction (2 papers, 2015 to 2025). A type of ILEUS, a functional not mechanical obstruction of the INTESTINES. "X-linked intestinal pseudo-obstruction due to filamin A mutation should be also considered in the differential diagnosis of SMIC." (PMID 26943384, 2015).
invasive breast carcinoma (2 papers, 2013 to 2021). A carcinoma that infiltrates the breast parenchyma. "By using a newly developed antibody that recognizes secreted variant of filamin-A, gradually increased levels of filamin-A was detected in normal breast tissue, localized and invasive breast cancer, which is associated with cancer progression." (PMID 23388158, 2013).
ischaemia (2 papers, 2022 to 2024). "While this is not direct evidence of the importance or relevance of filamin A O-GlcNAcylation functionally, it does open the potential for investigation of specific filamin A O-GlcNAcylation in apt rodent models of cardiac ischaemia reperfusion injury." (PMID 38958472, 2024). "Here we show, using transgenic mice expressing either constitutively edited or constitutively uneditable filamin A that filamin A editing critically controls angiogenesis in tumors but also in a mouse ischemia model." (PMID 36457700, 2022).
liver fibrosis (2 papers, 2017 to 2025). "Validated by Western blotting in CCl4-induced liver fibrosis development and regression, the expression of Filamin A and LASP1 protein were found increased as the expression of α- SMA and the expression of NAMPT in liver fibrosis was decreased." (PMID 28322315, 2017).
medulloblastoma (2 papers, 2017 to 2021). A malignant, invasive embryonal neoplasm arising from the cerebellum. "WNT-positive medulloblastomas were strongly linked to nuclear and cytoplasmatic immunoreactivity for b-catenin, filamin A, and YAP1, whereas SHH-activated tumors showed immunoreactivity for GAB1, YAP1, and filamin A." (PMID 33497354, 2021). "In primary medulloblastoma tissues, these groups are thought to be distinguishable using the immunohistochemical detection of β-catenin, filamin A, GAB1 and YAP1 protein markers." (PMID 28231263, 2017). "In this study, we investigated the possibilities of using the intracellular protein markers GAB1, β-catenin, filamin A, and YAP1 for the determination of defined molecular subgroups of medulloblastoma under in vitro conditions." (PMID 28231263, 2017).
metastatic tumors (2 papers, 2020 to 2022). "Other mutations included KDM5C (1/6, OVA_013), FLNA (1/6, OVA_378), RGS7 (1/6, OVA_047) and SPRY2 (1/6, OVA_365), which were also clonal in both primary and metastatic tumours." (PMID 32099096, 2020).
Mitral regurgitation (2 papers, 2021 to 2024). An abnormality of the mitral valve characterized by insufficiency or incompetence of the mitral valve resulting in retrograde leaking of blood through the mitral valve upon ventricular contraction. "FLNA is a gene known for CVDs, as mutations in FLNA can lead to cardiological phenotypes with aortic or mitral regurgitation." (PMID 34774109, 2021).
neuroendocrine tumors (2 papers, 2017 to 2022). "Since Rap1 small GTPase is involved in the control of cell migration and adhesion and it plays a key role in neuroendocrine tumors, we hypothesized that the effects of FLNA could be mediated, at least in part, by a modulation of Rap1 expression." (PMID 29100390, 2017).
osteoporosis (2 papers, 2015 to 2020). A condition of reduced bone mass, with decreased cortical thickness and a decrease in the number and size of the trabeculae of cancellous bone (but normal chemical composition), resulting in increased fracture incidence. "The results of the current study also showed that CTNNB1 and CAV1 were significantly downregulated in the osteoporosis samples, while SHC1, AKT1 and FLNA were upregulated." (PMID 25815782, 2015).
parathyroid tumors (2 papers, 2021 to 2023). "This is relevant in the setting of parathyroid tumors due to the X chromosome harboring loci for the FLNA and KDM5C genes." (PMID 36900197, 2023). "FLNA expression has also been investigated in parathyroid tumors, with unclear conclusions." (PMID 36900197, 2023). "Filamin A binds to and promotes activation of RhoA; therefore, filamin A and Gαq/11 downregulation occurring in parathyroid tumors may inhibit RhoA activation and the inhibitory effect of the Hippo signaling pathway on YAP1, contributing to reduction in YAP1 nuclear accumulation." (PMID 33670622, 2021). "In parathyroid tumors, Gαq/11 and FLNA/filamin A are downregulated at mRNA and protein levels." (PMID 33670622, 2021).
Patent ductus arteriosus (2 papers, 2015 to 2025). In utero, the ductus arteriosus (DA) serves to divert ventricular output away from the lungs and toward the placenta by connecting the main pulmonary artery to the descending aorta. "Chronic intestinal pseudo–obstruction (CIPO), thrombcytopaenia, patent ductus arteriosus (PDA), malrotation were found in two families with the duplications involved only the FLNA gene." (PMID 26672597, 2015).